AFP (alpha fetoprotein)
Diseases named in the same sentence as AFP in open-access papers (continued):
Sharing a sentence is not in itself a finding about the gene and the disease.
hepatoblastoma (continued). "Serum PIVKA-II and AFP levels were compared between the patients in the hepatic mass group and the patients in the control group and between the patients in the hepatoblastoma group and the patients in the hemangioendothelioma group." (PMID 38622445, 2024). "All tumoroids at early passage showed expression of known hepatoblastoma markers, AFP, DLK1, and the Wnt target gene, AXIN2." (PMID 39567523, 2024). "Hepatoblastomas with high expression levels of stem/progenitor cell markers (EpCAM, LIN28B, SALL4, HMGA2, AFP) are usually associated with poor prognosis." (PMID 37414763, 2023). "The traditional factors: AFP, PRETEXT stage, risk stratification and the presence of metastases have long been identified as major prognostic factors for hepatoblastoma." (PMID 37124183, 2023). "The most useful laboratory test for hepatoblastoma is alpha-fetoprotein (AFP), showing abnormal elevation in 80–90% of patients, and therefore serving as a sustainable biomarker for diagnosis, monitoring, and disease follow-up." (PMID 38066809, 2023). "Hepatoblastoma with small cell undifferentiated histology can mimic MRTL and show normal AFP levels but lack INI-1 mutations." (PMID 38132242, 2023). "While AFP has been a traditional biomarker for hepatoblastoma, its limitations in sensitivity and specificity underscore the need for adjunctive markers like ctDNA." (PMID 38201440, 2023). "Changes to AFP values and imaging studies are the current mainstay for treatment monitoring and relapse surveillance in hepatoblastoma." (PMID 38201440, 2023). "Factors with a negative impact on the long-term outcome are a reduced response to neoadjuvant chemotherapy as expressed by a smaller decrease of AFP in the subgroup of hepatoblastoma patients and transplantation as salvage transplantation." (PMID 36832331, 2023). "Hepatoblastoma with low levels of AFP is considered aggressive and has abysmal prognosis or is associated with the small cell undifferentiated (SCUD) subtype." (PMID 38066809, 2023). "Liuet al. developed a magnetic bead separation platform consisting of a switching aptamer-triggered hybridization chain reaction (SAT-HCR) and the CRISPR-Cas12a sensor for alpha fetoprotein (AFP), a marker of hepatoblastoma." (PMID 37528660, 2023). "Hepatoblastoma should be considered when alpha-fetoprotein levels show a significant elevation in newborns." (PMID 37520052, 2023). "Hepatoblastoma usually presented with a large abdominal mass and increased alpha‐fetoprotein (AFP) value." (PMID 33236528, 2021). "The cornerstones of surveillance in BWSp are abdominal ultrasound (US) for early detection of WT and the serum alpha-fetoprotein assay used for early diagnosis of hepatoblastoma." (PMID 34944785, 2021). "Analysis showed that the recurrence of hepatoblastoma was often accompanied by distant metastases and abnormally elevated serum AFP levels." (PMID 34843510, 2021). "The US can detect also hepatoblastoma at advanced stages with respect to alpha-fetoprotein, as well as other rarer abdominal neoplasms." (PMID 34944785, 2021). "The typical clinical symptoms of hepatoblastoma are alpha-fetoprotein (AFP) rising and abdominal mass." (PMID 34367972, 2021). "The position of experts on US screening in patients with IC2-LoM and on screening for hepatoblastoma by means of the alpha-fetoprotein assay, on the other hand, appears varied." (PMID 34944785, 2021). "The increase in serum AFP plays an important role in the diagnosis of hepatoblastoma, and the change in serum AFP value is important for predicting the outcome of children with hepatoblastoma." (PMID 34843510, 2021). "Monitoring serial serum AFP levels can allow for early detection of hepatoblastoma, even before detection by abdominal imaging, which can lead to better patient outcomes." (PMID 32039119, 2019).
hepatoblastoma (continued). "For some tumors, metabolites are being used to monitor patients, similar to hepatoblastoma, where an elevated level of AFP is considered both a biomarker and prognostic factor." (PMID 31817982, 2019). "AFP screening can be used to distinguish hepatoblastoma from infantile hepatic hemangioma, a benign vascular neoplasm." (PMID 32039119, 2019). "An alpha-fetoprotein level < 1200 ng/mL after neoadjuvant chemotherapy and age at hepatoblastoma diagnosis ≤1.25 years are both predictors of better overall and native liver survival in hepatoblastoma patients." (PMID 28851352, 2017). "Hepatoblastoma subjects with a high initial serum AFP level and decreases to <1200 ng/mL after neoadjuvant chemotherapy is a good clinical prognostic marker." (PMID 28851352, 2017). "While the 5- and 10-year overall survival rates were 50% and 50%, respectively, of hepatoblastoma subjects with an AFP level ≧ 1200 ng/mL after SIOPEL neoadjuvant chemotherapy." (PMID 28851352, 2017). "All study subjects included in this study had high initial serum AFP levels at the diagnosis of hepatoblastoma." (PMID 28851352, 2017). "While the 5- and 10-year native liver survival rates were 40% and 40%, respectively, of hepatoblastoma subjects with an AFP level ≧ 1200 ng/mL after SIOPEL neoadjuvant chemotherapy." (PMID 28851352, 2017). "A low initial serum AFP level (<100 ng/mL) at the diagnosis of hepatoblastoma was reported to be a poor prognostic indicator." (PMID 28851352, 2017). "The 5- and 10-year native liver survival rates were 95% and 75%, respectively, of hepatoblastoma subjects with an AFP level < 1200 ng/mL after SIOPEL neoadjuvant chemotherapy." (PMID 28851352, 2017). "The 5- and 10-year overall survival rates were 95% and 85%, respectively, of hepatoblastoma subjects with an AFP level < 1200 ng/mL after SIOPEL neoadjuvant chemotherapy." (PMID 28851352, 2017). "Here we demonstrate that an age at diagnosis ≤1.25 years and serum AFP levels <1200 ng/mL after SIOPEL neoadjuvant chemotherapy are both predictors of better overall and native liver survival of patients with hepatoblastoma with high initial serum AFP levels." (PMID 28851352, 2017). "The alpha-fetoprotein (AFP) level in particular is key, as this is elevated in the majority of patients with hepatoblastomas and HCCs." (PMID 27526937, 2016). "With the preliminary diagnosis of neuroblastoma or hepatoblastoma, serum alpha-fetoprotein (AFP) and urine vanillylmandelic acid (VMA) were analyzed." (PMID 25805677, 2015). "The complete excision of the hepatoblastoma determines the decrease of the AFP serum level, which will be normalized after 4–6 weeks." (PMID 25525545, 2014). "When suspicious exists, serum AFP is a good guide in differentiating hepatoblastoma from mesenchymal hamartoma." (PMID 25013683, 2014). "Characteristic imaging and histopathological and AFP levels help in the diagnosis of hepatoblastoma." (PMID 25525545, 2014). "AFP levels are nearly always elevated in hepatoblastomas and are correlated in most cases with the stage of the disease; also the rate of decline of AFP during treatment is of prognostic value." (PMID 19909520, 2009). "Clinical investigation revealed that the prognosis of children with hepatoblastoma correlates with multifocal growth in the liver, invasion of blood vessels, distant metastasis, and either very low or high levels of serum AFP." (PMID 15280920, 2004). "This study indicates that high AFP levels may serve as a laboratory finding to support the diagnosis of hepatoblastoma in this age group." (PMID 39961817, 2025). "Furthermore, it is advised to measure serum AFP every three months until the age of four, as 90% of hepatoblastoma cases occur during this period." (PMID 40959375, 2025). "Western blot analysis showed the decreased expression of HB‐associated genes like AFP, OCT4, GPC3, and DUSP9 in IGF2 KD HepG2 cells, indicating that decreasing IGF2 could reduce hepatoblastoma stemness." (PMID 40271711, 2025).
hepatoblastoma (continued). "Western blot analysis showed that Fatostain treatment decreased the expression of HB‐associated genes like AFP, OCT4, GPC3, and DUSP9, indicating that SREBF2 inhibition could reduce hepatoblastoma stemness." (PMID 40271711, 2025). "Despite negative AFP, anaplastic hepatoblastoma was considered in this 3-year-old, and SIOPEL high-risk protocol initiated." (PMID 40560480, 2025). "RT‐PCR analysis showed the increased expression of HB‐associated genes like AFP, GPC3, and DUSP9, indicating that SREBF2 could enhance hepatoblastoma stemness." (PMID 40271711, 2025). "Concurrently, we conducted a comparative analysis of serum AFP levels in the hepatoblastoma group." (PMID 40271711, 2025). "The Western blot analysis of IGF2‐treated cells demonstrated increased activation of the IGF2‐related signaling pathway and the increased expression of HB‐associated proteins, including AFP, OCT4, GPC3, DUSP9, and cMYC, indicating IGF2's role in sustaining hepatoblastoma stemness." (PMID 40271711, 2025). "Consequently, AFP serves as a critical tumor marker for hepatoblastoma (HB), playing a vital role in both diagnosis and prognostic evaluation." (PMID 41333206, 2025). "In addition, AFP has not only been used for diagnosis, but has recently been advocated as a surveillance marker for relapse in children with AFP-positive hepatoblastomas." (PMID 40504251, 2025). "Hepatoblastoma is a secretory tumor and demonstrates elevated serum alpha-fetoprotein (AFP) levels." (PMID 38831055, 2024). "AFP levels in hepatoblastoma patients were within normal range." (PMID 39906731, 2024). "Nonetheless, there are rare instances where hepatoblastoma may present with low serum AFP or only mildly elevated levels, and HMH might also exhibit a predominantly solid appearance." (PMID 39737275, 2024). "A mild to moderate elevation in AFP levels associated with a hepatic mass in a child is not sufficient to conclusively diagnose hepatoblastoma." (PMID 39737275, 2024). "Hence, based on CT imaging, a possible differential of pediatric hepatic lesions such as hepatic mesenchymal hamartoma and other less likely possibilities of hepatoblastoma were considered in view of mildly raised AFP levels." (PMID 39737275, 2024). "Clusters 0, 2, and 4, characterized by high expression of known hepatoblastoma markers, including AFP, DLK1, and GPC3, were shared among all the tumoroids, while the remaining clusters of cells were more heterogeneously represented across the different tumoroids." (PMID 39567523, 2024). "In other words, a significantly elevated AFP level in newborns with hepatoblastoma is concerning." (PMID 38792380, 2024). "When rhabdoid tumors are correctly diagnosed with testing for loss of SMARCB1, neither hepatoblastoma with small cell undifferentiated component nor alpha-fetoprotein less than 100 ng/mL confer poor prognosis." (PMID 36672416, 2023). "A common tumor marker for hepatoblastoma screening and diagnosis is alpha-fetoprotein (AFP)." (PMID 36997898, 2023). "AFP has been widely used to monitor the recurrence and treatment effect of hepatoblastoma." (PMID 37124183, 2023). "There are several potential advantages of ctDNA over AFP testing in hepatoblastoma." (PMID 38201440, 2023). "We could not only mimic characteristic growth of hepatoblastoma cells on and in the matrix, but also the formation of distinctive three-dimensional, vital, AFP-positive tumours." (PMID 38076431, 2023). "Additionally, the authors detected high blood AFP levels in an Arabian filly with hepatoblastoma confirmed post‐mortem." (PMID 36495211, 2023). "A recent large study describing outcome and risk factors for 175 pediatric patients who had transplants due to liver tumors in North America identified AFP decrease, low post-transplant AFP in hepatoblastoma patients and younger age in patients with HCC as factors favoring event-free survival." (PMID 36832331, 2023).
hepatoblastoma (continued). "In many European countries, the IC2-LoM group is not screened as it has almost no risk for WT and alpha-fetoprotein screening is not adopted given the overall low-risk of hepatoblastoma (less than 5%)." (PMID 34944785, 2021). "Luciferase-expressing HepG2 human hepatoblastoma cells were orthotopically implanted in the livers of athymic nude mice, and tumor establishment was verified at 6 weeks after implantation by bioluminescent imaging and serum AFP concentration." (PMID 31636665, 2019). "Further longitudinal studies are needed to determine whether AFP can be used in predicting the prognosis of hepatoblastoma." (PMID 31651371, 2019). "On the fourth visit (+29 weeks), his serum AFP level was elevated to >200,000 ng/ml and abdominal computer tomography scan revealed a well-defined heterogeneous liver mass (6.5 × 6.2 cm) suspicious of a hepatoblastoma." (PMID 29190888, 2017). "AFP level was checked according to the schedule, while ultrasonography was not, because the parents did not follow the instructions properly, which resulted in the delay of diagnosis of hepatoblastoma by two months." (PMID 29190888, 2017). "This study raises the hypothesis that in hepatoblastomas, the addition of IL-12 from the virus to the tumor bed may help to counteract some the effects of AFP upon the host’s immune system and lead to enhanced tumoricidal activity of the virus." (PMID 24497984, 2014). "AFP level is a valuable tumour marker to see response of presurgical chemotherapy, in the evaluation of the excision result and for the precocious diagnosis of the hepatoblastoma relapse." (PMID 25525545, 2014). "If we would have measured serum AFP in our patient, we could make the correct diagnosis preoperatively, because AFP increases largely in hepatoblastoma." (PMID 25013683, 2014). "In another report, Jassam and colleagues described a two-month-old infant with a liver tumor whose diagnosis and subsequent management was changed from hepatic haemangioendothelioma to hepatoblastoma after discovery of a falsely low alpha-fetoprotein (AFP) measurement." (PMID 24088261, 2013). "The decrease of AFP during chemotherapy, despite an increase in tumor size in our case, is at first sight unusual, but most likely reflects a rather high chemosensitivity of the hepatoblastoma tumor portions." (PMID 19909520, 2009). "Consequently, due to the associated tumor risk, early screening for neoplasms is recommended, using abdominal ultrasounds (aimed at identifying renal tumors, particularly Wilms tumor) and serum AFP tests (targeted at detecting liver tumors, especially hepatoblastoma)." (PMID 40959375, 2025). "Thus, changes in AFP levels following the start of relapse treatment appear to provide a prognostic guide for future outcomes, as has been found to be the case during the initial treatment of hepatoblastoma patients." (PMID 38398087, 2024). "However, at present, very little data comparing ctDNA to AFP in hepatoblastoma are available." (PMID 38201440, 2023). "Moreover, AFP staining and Live/Death staining proved the manifestation of a vital hepatoblastoma." (PMID 38076431, 2023). "In an experimental model (xenografted hepatoblastoma), the administration of aprepitant (80 mg/kg/day for 24 days) decreased the weight and tumor volume, the vascularized area, the serum level of tumor-specific alpha-fetoprotein (a marker of hepatoblastoma) and the number of cells expressing Ki-67." (PMID 32962202, 2020). "The small patient numbers to date mean that further evaluation will be required to establish whether there is any association between genetic and environmental factors that contribute to the clinical outcome of serum AFP levels in different subsets of Asian patients with hepatoblastoma." (PMID 31540387, 2019). "Hence, the cutoff diagnostic age and cutoff initial AFP reported recently did not act as feasible prognostic indicators in our hepatoblastoma population in Taiwan." (PMID 28851352, 2017).
hepatoblastoma (continued). "Small cell undifferentiated subtypes of hepatoblastomas may not be associated with raised AFP levels." (PMID 27526937, 2016). "HUH6 and HepG2 cells exhibited stronger transcriptomic activation of AFP, DUSP9, GPC3, DLK1, MYC compared to other non‐hepatoblastoma cell lines." (PMID 40271711, 2025). "The results showed that the combination of PIVKA-II and AFP further increase the efficiency for the diagnosis of childhood hepatic tumors (AUROC = 0.891) and for the differentiation of hepatoblastoma from benign hepatic tumors (AUROC = 0.895)." (PMID 38622445, 2024). "Other preclinical and clinical examples have been developed, including a scFv-CAR-T cell therapy targeting alpha-fetoprotein (AFP), currently in Phase I/II trials for the treatment of pediatric hepatoblastoma." (PMID 39594730, 2024). "Serum AFP levels to screen for hepatoblastoma should be interpreted in the context of the clinical picture, and patients with BWS tend to have higher AFP levels in early childhood compared to normal pediatric values." (PMID 32039119, 2019). "Hence, subjects with earlier hepatoblastoma onset (≤1.25 years) may have greater chemosensitivity, a greater likelihood of AFP levels <1200 ng/mL after neoadjuvant chemotherapy, and thus improved native liver and overall survivals as compared with those diagnosed after 1.25 years." (PMID 28851352, 2017). "As per the German Society of Pediatric Hematology and Oncology (GPOH) in children below 3 years, a suspected case of hepatoblastoma with highly elevated AFP can be treated as hepatoblastoma without a biopsy." (PMID 38831055, 2024). "The diagnosis was revised to hepatoblastoma or rhabdoid or retained as indeterminate after AFP correlation, given that rhabdoid tumors will not have raised AFP levels." (PMID 38831055, 2024). "We observed a higher accuracy of 89.8% for our hepatoblastoma subset of patients on imaging without AFP correlation, which increased to 96.6% with AFP correlation." (PMID 38831055, 2024). "In the previous reports, tumor stage, alpha-fetoprotein (AFP), histological type, type of radical surgery, metastasis, and adjuvant therapy such as chemoradiation were proposed to be the prognostic indicators in hepatoblastoma." (PMID 37124183, 2023). "Similar to the function of AFP, we speculate whether NLR can be used for the detection of therapeutic efficacy of hepatoblastoma and the monitoring of tumor recurrence, which still needs further research." (PMID 37124183, 2023). "Moreover, staining for the alpha-fetoprotein (AFP), an established marker for liver tumours, proved the preservation of the disease phenotype of hepatoblastoma." (PMID 38076431, 2023). "Clinical and laboratory investigations include serum alpha-fetoprotein (AFP), which may be elevated in up to a third of cases (similarly to hepatoblastoma); therefore, AFP is critical for diagnosis and monitoring the disease as a tumour marker." (PMID 37190144, 2023). "The initial diagnosis of hepatoblastoma was not well-supported by the relatively low level of AFP in this patient." (PMID 36551543, 2022). "The consensus group stated that AFP measurements should not be offered routinely because of the low incidence of hepatoblastoma in BWSp and the difficulties in interpretation." (PMID 32039119, 2019). "All cell cultures were found to secrete alpha-fetoprotein, a defining characteristic of hepatoblastoma which is not present in fully differentiated, non-regenerating hepatocytes." (PMID 31741706, 2019). "We first performed a transcriptomic evaluation of the two well‐recognized hepatoblastoma cell lines, HepG2 and HUH6, using Pearson's analysis with gene signatures in the public GSE168997 dataset to elucidate IGF2′′s role in hepatoblastoma (AFP, DUSP9, GPC3, DLK1, MYC, EPCAM, KRT8, and LIN28B)." (PMID 40271711, 2025).